NRAS (NRAS proto-oncogene, GTPase)
Diseases named in the same sentence as NRAS in open-access papers (continued):
Sharing a sentence is not in itself a finding about the gene and the disease.
melanoma (continued). "GAB2, found to be amplified in 30.6% of acral melanomas and 17.1% of mucosal melanomas, has been shown to induce tumour angiogenesis by regulating hypoxia inducible factor 1 subunit alpha (HIF‐1α) and VEGF expressions in NRAS‐driven melanoma." (PMID 39757723, 2025). "Our results corroborate these findings, showing that modulation of the respiratory chain can sensitize NRAS mutant melanoma cells to vemurafenib action." (PMID 40141318, 2025). "Strong dependencies to NRAS-mRNA expression were also observed in multiple NRAS-mutant cancer cell lines of non-melanoma cancers (i.e., Neuroblastoma, Acute Myeloid Leukemia, Ovarian cancers, and Small Cell Lung Cancer)." (PMID 40473796, 2025). "Experts use genetic markers and especially changes in BRAF and NRAS genes, to learn more about how melanoma develops and progresses." (PMID 41049012, 2025). "NRAS-mutant melanoma is difficult to treat due to resistance to current therapies like MEK inhibitors." (PMID 40563669, 2025). "In a phase I trial in pretreated NRAS mutant melanoma patients, the pan-RAF inhibitor naporafenib was combined with trametinib and an objective response rate of 46% was achieved." (PMID 40361349, 2025). "Mutations in the Aurka inhibitor PPP6 C (protein phosphatase 6 catalytic subunit) gene are also typical in BRAF and NRAS mutant melanomas." (PMID 40361349, 2025). "Here, we present on the efficacy of targeting NRAS-mRNA using GapmeR ASOs as a highly selective and efficient approach to combat NRAS-mutant melanoma." (PMID 40473796, 2025). "Accurate diagnosis of dedifferentiated melanoma demands a high level of suspicion and comprehensive sampling to identify either a conventional melanoma precursor or mutations consistent with melanoma, such as BRAF, NRAS, or NF1." (PMID 39625060, 2025). "To investigate the cellular distribution of NRAS-mRNA, we conducted subcellular fractionation analysis in two NRAS-mutant melanoma cell lines (D04 and MM415)." (PMID 40473796, 2025). "MEK inhibitors should not be combined with AKT inhibitors because they are ineffective in NRAS mutant melanoma." (PMID 40361349, 2025). "In contract, the adoption of ddPCR for detecting common melanoma mutations including BRAF, NRAS, KIT, and TERT significantly improved sensitivity, allowing ctDNA to be distinguished from total cfDNA in approximately 80% of melanoma patients." (PMID 39859576, 2025). "To investigate the molecular factors influencing this response, we analysed the genomic and transcriptomic characteristics of NRAS mutant mucosal melanoma." (PMID 39757723, 2025). "On one hand, common genetic mutations in melanoma, such as BRAF, NRAS, and NF1, result in multiple potential resistance pathways within the MAPK signaling axis." (PMID 40599859, 2025). "In terms of molecular characteristics, 86 patients (52.7%) displayed BRAF mutation (100% in the TT group vs. 7.4% in the IT group, p < 0.001), while 33 patients exhibited NRAS mutant melanoma (39.5% in the IT group vs. 1.2% in the TT group, p < 0.001)." (PMID 39272953, 2024). "The most common is the NRAS and BRAF oncogenes, with a high number of melanoma cases demonstrating the BRAF V600 mutation." (PMID 39768392, 2024). "Human melanomas are often driven by well-defined genetic mutations (e.g., BRAF, NRAS, and KIT mutations) that can be targeted by specific therapies." (PMID 39408717, 2024). "Recent studies in a zebrafish melanoma model suggest that p38 MAPK functions as a tumor suppressor in NRAS-mutant melanomas." (PMID 38300709, 2024).
melanoma (continued). "This review explores the intricate interplay between genetic alterations, such as mutations in BRAF, NRAS, and KIT, and melanoma pathogenesis." (PMID 39200315, 2024). "Phospho-proteomic analysis has identified >1,100 proteins that are differentially regulated in NRAS-G12V and Q61L-mutant melanoma." (PMID 39372214, 2024). "In melanomas, the hyperactivation of the MAPK pathway is mainly through activating mutations in BRAF, NRAS, NF1, and KIT." (PMID 38247727, 2024). "The search terms “melanoma”, “mutation”, “surgery”, and “metastatic melanoma” and specific gene names (TMB, BRAF, NRAS, EGFR, c-KIT, MITF, etc.)were used in combination with the Boolean operators AND or OR." (PMID 38534309, 2024). "Although all BRAFi efficiently impeded ERK phosphorylation in BRAF-mutant and BRAF-WT melanoma cells, their effect on MAPK signaling in endothelial cells resembled the effect in melanoma cells with upstream NRAS mutations." (PMID 38839106, 2024). "The NRAS gene, like BRAF, is a crucial component of the MAPK pathway and is implicated in 15% to 20% of melanoma cases." (PMID 38534742, 2024). "MEK inhibitors (MEKi) were shown to be clinically insufficiently effective in patients suffering from BRAF wild-type (BRAF WT) melanoma, even if the MAPK pathway was constitutively activated due to mutations in NRAS or NF-1." (PMID 38263136, 2024). "The cell lines were representative of the three most common mutations detected in melanoma: A375 harbors a mutation for BRAF, Mel224 a mutation for NRAS, and the CHL-1 line is wild type for these two genes." (PMID 38892279, 2024). "Both experienced benefits, but with a notably more synergistic and narrow dosage range for NRAS mutant melanoma (mean Bliss score of 0.27 in NRAS vs. 0.1 in BRAF mutants)." (PMID 39199684, 2024). "Mutations in BRAF, NRAS, NF1, and CKIT are sometimes referred to as “driver” mutations, as they rarely overlap each other in melanoma cells." (PMID 38339344, 2024). "All NRAS-mutant melanomas demonstrated IC50 values in the micromolar range, with a 3-fold average lower sensitivity to corin versus BRAF-mutant melanomas." (PMID 38300709, 2024). "One tumor with an NRAS G12R mutation had an intrachromosomal chromothripsis event spanning KRAS, while BRAF and NF1 were involved in chromothripsis events in one NRAS melanoma each." (PMID 38758740, 2024). "RAC1 mutations are present in 2–9% melanomas, usually in association with activation mutations in BRAF or NRAS, or inactivating mutations in NF1." (PMID 40396280, 2024). "The results showed that both BRAF- and NRAS-mutant melanoma cultures were viable after 24 h treatments despite the significant impact of RocA on protein synthesis." (PMID 39436655, 2024). "successfully created several zebrafish ‘Fin’ melanoma systems that are driven by genes such as CRKL, GAB2 and NF1, analogous to human melanomas that lack BRAF/KIT/NRAS alterations." (PMID 39627834, 2024). "This study showed that equine malignant melanoma (EMM) cells (MelDuWi) harbor the KRAS p.Q61H mutation, while canine malignant melanoma (CMM) cells (cRGO1 and cRGO1.2) carry NRAS p.G13R." (PMID 38397192, 2024). "Common mutations in melanoma are BRAF and NRAS, but, in addition, approximately 70% of mutations in melanoma involve the mitogen-activated protein kinase (MAPK) pathway." (PMID 38893071, 2024). "Due to reports indicating the role of NRAS in resistance to vemurafenib, its level was measured in the BRAFi/MEKi-resistant melanoma cell lines." (PMID 39175042, 2024). "Although the effect of Mb24 on oncogenic NRAS-mediated activation of ERK in melanoma cells is rather modest, these findings are in agreement with prior published studies." (PMID 39379700, 2024). "NRAS mutations are typically mutually exclusive of BRAF mutations, reinforcing their unique role in melanoma’s molecular pathology." (PMID 38474231, 2024). "The NRAS-driven melanomas pose a particular challenge as they cannot be treated by the combinations of BRAF and MEK inhibitors." (PMID 39436655, 2024).
melanoma (continued). "We analyzed the pharmacokinetic and tumor growth data from Phase 1 clinical trials of Belvarafenib with Cobimetinib to show that the synergy requirement imposes stricter precision dose constraints in NRAS mutant melanoma patients." (PMID 39199684, 2024). "Our characterization of T-RECS as an actionable vulnerability shows that lncRNAs are therapeutically tractable, and that ASO-based RNA-targeting strategies can suppress the growth of NRAS/MAPK-driven melanoma tumors." (PMID 38383439, 2024). "Three of them had not been detected by previous routine testing (ATM p.R1730* in GE21 pancreatic tumor, NRAS p.Q61K in GE15 melanoma, and BRAF p.V600E in GE01 undifferentiated embryonal sarcoma of the liver)." (PMID 38750555, 2024). "The genomic profiling of melanoma tumors revealed several recurrent mutations involved in their pathogenesis and evolution, such as BRAF, NRAS, and KIT, contributing to these tumors’ genomic subtyping." (PMID 38396984, 2024). "We have shed light on this aspect in our retrospective analysis of the mutational landscape via NGS in melanoma, particularly focusing on the RAF and NRAS mutations." (PMID 38470950, 2024). "A total of 42% had BRAFnon-V600K melanoma, 14% had BRAF V600K tumors, 18% had NRAS mutations, and 26% were wild-type for both BRAF and NRAS." (PMID 38339344, 2024). "Our findings reveal a more synergistic but narrower dosing landscape in NRAS vs. BRAF mutant melanoma, which we link to a mechanism of adaptive resistance through negative feedback." (PMID 39199684, 2024). "A study of whole-genome sequences from cutaneous, acral, and mucosal subtypes of melanoma in 183 melanoma samples found that BRAF, NRAS, and NF1 were significantly mutated genes in AM, while SF3B1 (splicing factor 3B subunit 1) was identified in MM." (PMID 38469235, 2024). "The OFA has been specifically designed to provide comprehensive genomic profiling of solid tumors and includes the mutational study of melanoma-related genes such as BRAF, NRAS, KIT, MAP2K1, or HRAS." (PMID 39000050, 2024). "To further validate the involvement of ATP1A1 in resistance to BRAF-targeted therapy, we conducted experiments using three different models of melanoma cell lines (harbouring mutations in cKIT, BRAF or NRAS)." (PMID 38178183, 2024). "Acral melanomas display a profile of driver mutations similar to that observed in cutaneous melanomas, with BRAF being the most frequently mutated, followed by NRAS and NF1 mutations." (PMID 39727691, 2024). "This type of melanoma rarely presents mutations in the BRAF and NRAS genes, common in other melanomas, but has a high frequency of mutations in the KIT gene, which can activate the MAPK signaling pathway." (PMID 39202970, 2024). "NGS allows for the comprehensive screening of multiple genes associated with melanoma in a single experiment, enabling the efficient identification of mutations in key genes such as BRAF, NRAS, and c-KIT." (PMID 38474231, 2024). "Mutations in the B-Raf proto-oncogene (BRAF) and neuroblastoma RAS viral oncogene homolog (NRAS), common in other melanomas, are less frequent in this variant." (PMID 39202970, 2024). "BRAF, NRAS, and C-KIT mutations are, nevertheless, often less common in DM than in other forms of melanoma." (PMID 39872575, 2024). "In parallel, belvarafenib, a pan-RAF inhibitor, has been shown to encourage anticancer activity in preclinical melanoma models and patients with BRAF and NRAS mutations." (PMID 39582535, 2024). "Melanomas that arise against a background of low-CSD typically harbor BRAF V600E mutations (and rarely NRAS Q61 mutations) and originate from benign nevi." (PMID 38396984, 2024). "The patients with NRAS-mutant melanoma exhibited a heightened response rate and experienced clinical benefit from immune therapy." (PMID 39195270, 2024). "The known genetic drivers of melanoma include B-raf proto-oncogene (BRAF), neurofibromin 1 (NF1), and NRAS mutations." (PMID 38399429, 2024).
melanoma (continued). "Knockdown of CD133 expression in NRAS-mutant melanoma promoted cell apoptosis and improved trametinib efficacy in the NRAS-mutant cells." (PMID 38732242, 2024). "NF1-mutated melanomas typically arise on chronically sun-exposed skin or in older individuals, exhibit a high mutation burden, and lack BRAF or NRAS mutations." (PMID 38891988, 2024). "Melanomas fall into 4 genomic categories based on driver mutations: BRAF (50%), NRAS (25%), or NF1 (15%) mutant and triple WT." (PMID 38319712, 2024). "The BRAF mutant is the most common mutant type of melanoma, accounting for over 60% of all cases, and NRAS and NF1 have also been found as common mutation sites in melanoma." (PMID 39659781, 2024). "This reduced cell proliferation in melanoma cell lines and inhibited tumour progression in xenograft melanoma NRas-mutant mouse models (determined through ex vivo Ki67 staining), which was associated with a decrease of ERK phosphorylation." (PMID 39372214, 2024). "Brain metastasis is a common and severe complication in melanoma patients with BRAF and NRAS mutations, often resulting in a poor prognosis." (PMID 39582535, 2024). "It has been demonstrated that patients with NRAS mutant melanoma were older than 55 years and had a previous history of UV exposure, and thus, higher pro-inflammatory conditions than those with BRAF mutant tumors." (PMID 38396984, 2024). "NRAS mutant melanoma demonstrated significantly decreased overall survival on multivariable analysis (HR for death 2.95, 95% CI 1.13–7.69, p = 0.027, log-rank test) compared with other TCGA molecular subgroups." (PMID 38611025, 2024). "We utilized ulixertinib, a 1st-in-class ERK inhibitor that has shown single-agent activity in NRAS-mutant melanoma patients." (PMID 38509064, 2024). "Our retrospective study has highlighted the value of NGS in detecting BRAF, NRAS mutations and RAF fusions, extending the possibilities for targeted therapies in malignant melanoma." (PMID 38470950, 2024). "These inquiries have illustrated the occurrence of mutations in genes like PIK3A, NRAS, MAP2K1, and AKT1 among patients with melanoma undergoing targeted therapy." (PMID 38539531, 2024). "At the molecular level, it is supposed that somatic mutations in NRAS and BRAF, which occur mutually exclusive, are critical in this multistep development of melanoma." (PMID 38396984, 2024). "In melanoma, BRAF and NRAS mutations promote cell proliferation by activating the MAPK/ERK pathway, while CDKN2A mutations further enhance tumor cell proliferation by removing inhibition of the cell cycle." (PMID 39581873, 2024). "Despite both NRAS and BRAF mutations being fairly common in the development of melanoma, rarely do both mutations occur in the same patient." (PMID 38534742, 2024). "Pharmacological inhibitors of STK19 in turn blocked NRAS phosphorylation and interrupted melanoma cell growth." (PMID 39512309, 2024). "All the clinically relevant targets such as BRAF and NRAS have a comparable distribution thus suggesting the value of larger scale sequencing in melanoma." (PMID 38184610, 2024). "RAS oncogenes are driver genes in about 30% of melanoma cases, with NRAS being the dominant one, accounting for 25–28% of melanoma cases." (PMID 39340537, 2024). "Further studies are necessary to better evaluate the impact of NRAS and BRAF mutations on the response to ipilimumab in melanoma and to define the best treatment for these patients after iPD1 therapy failure." (PMID 39410017, 2024). "It is now known that certain subtypes of melanoma are associated with specific mutations (BRAF, KIT, and NRAS mutations)." (PMID 39335684, 2024). "At the molecular level, melanoma is driven by genetic mutations in key regulatory genes, including BRAF, NRAS, and c-KIT, which are implicated in cell growth, differentiation, and survival pathways." (PMID 39598801, 2024).
melanoma (continued). "Whereas, reflex NGS testing with an expanded panel also encompassing KRAS, KIT, and NRAS is only limited to ocular and mucosal melanomas." (PMID 39661469, 2024). "Somatic mutations in key melanoma oncogenes, such as BRAF or NRAS, are already present in benign nevi, indicating that they occur early during disease progression." (PMID 38396984, 2024). "The missense mutation of neuroblastoma RAS viral oncogene homolog (NRAS) occurs in 15%–20% of all patients and is correlated with a more aggressive melanoma subtype with elevated capacity for metastasis." (PMID 39086722, 2024). "Common mutations in NRAS and BRAF observed in melanoma activate the RAS/RAF/MAPK and PI3K/AKT signaling pathways." (PMID 38504984, 2024). "Particularly in melanoma cells, STK19 has been shown to activate oncogenic signaling pathways through selective phosphorylation of the RAS mutant variant (NRAS)." (PMID 39512309, 2024). "Treating NRAS-mutant melanoma poses considerable challenges, particularly for patients who do not respond to immunotherapy." (PMID 38891988, 2024). "In melanomas showing Spitz-like features, the presence of VE1 and/or NRAS Q61R IHC helps to confirm the conventional melanoma pathway alteration in BRAF V600E and/or NRAS Q61R, respectively." (PMID 38247727, 2024). "BRAF mutant tumors had the lowest median TMB (12.4 mutations/Mb), followed by NRAS mutant tumors (median 17.5 mutations/Mb) and TWT melanomas (28.2 mutations/Mb)." (PMID 38611025, 2024). "We chose a proteomic approach to assess the proportion of MAPK kinase substrates synthesized in an eIF4F-dependent manner in human BRAF- and NRAS-mutant melanoma cells." (PMID 39436655, 2024). "The MAPK pathway plays a pivotal role in melanoma biology, primarily through the mutational activation of key oncogenes such as BRAF and NRAS." (PMID 39199684, 2024). "Targeted therapies developed for melanoma include MAPK inhibitors, BRAFi and MEKi, These target the pathogenic constitutively activated MAPK pathway in BRAF- and NRAS- mutant melanoma cells." (PMID 38533720, 2024). "Belvarafenib exhibited robust melanoma growth suppression in mice with BRAFV600E mutations and significantly inhibited tumor progression in mice with NRAS mutations." (PMID 39582535, 2024). "Currently, clinical trials are exploring the efficacy of MEK inhibitors, either alone or in combination with pan-RAF inhibitors, CDK4/6 inhibitors, or focal adhesion kinase inhibitors, for the management of metastatic NRAS-mutant melanoma." (PMID 38891988, 2024). "Among the melanoma samples in our study, 12 exhibited BRAF mutations, and 11 had NRAS G12/G13 mutations." (PMID 38396984, 2024). "Five out of the seven melanoma brain metastases harbored the BRAF V600E mutation, and two out of the seven cases had other less frequent mutations (one NRAS mutation, one KIT mutation)." (PMID 39204387, 2024). "Instead, high-CSD melanoma is characterized by a more miscellaneous set of MAPK pathway mutations, such as BRAF V600K, NRAS, or KIT mutations, or inactivation of the negative regulators of Ras, NF1, or RASA2." (PMID 38247727, 2024). "The Cancer Genome Atlas has proposed a genetic classification of melanoma into four subtypes based on mutations in BRAF, NRAS, NF1 and triple-wild-type melanomas." (PMID 38903495, 2024). "We have shown that induced ectopic expression of CD133 alters the gene expression profile of two independent patient-derived NRAS mutant melanoma cell lines." (PMID 38727313, 2024). "Our study highlights the value of NGS in detecting BRAF, NRAS mutations and RAF fusions, expanding possibilities for targeted therapies in malignant melanoma." (PMID 38470950, 2024). "In the context of NRAS mutant superficial spreading melanoma, network modeling of tumor cells treated with MEKi has identified CDK4 as a key driver of therapy resistance." (PMID 38066089, 2024). "We have succeeded in determining the most common mutations in the BRAF, NRAS, and TERT genes that cause melanoma." (PMID 39195270, 2024).